NIN (ninein)
Description:
Centrosomal protein required in the positioning and anchorage of the microtubule minus-end in epithelial cells. May also act as a centrosome maturation factor. May play a role in microtubule nucleation, by recruiting the gamma-tubulin ring complex to the centrosome. Overexpression does not perturb nucleation or elongation of microtubules but suppresses release of microtubules. Required for centriole organization and microtubule anchoring at the mother centriole.
Synonyms: SCKL7
Tractability: Antibody: its Gene Ontology location is reachable by antibodies, with medium confidence. PROTAC: ubiquitination databases record sites on it; its protein half-life has been measured.
Gene: Protein-coding gene on chromosome 14 (50,719,763 to 50,831,504, reverse strand). Ensembl gene ENSG00000100503.
Subcellular location: Cytoplasm, cytoskeleton, microtubule organizing center, centrosome; Cytoplasm, cytoskeleton, microtubule organizing center, centrosome, centriole; Cell junction, desmosome; Cytoplasm (Isoform 6)
Subcellular location (Human Protein Atlas): Basal body; Centrosome; Nucleoli; Nucleoli rim
Gene Ontology:
Molecular function: protein binding; calcium ion binding
Biological process: centriole-centriole cohesion; intracellular protein localization; microtubule anchoring at centrosome; centrosome localization; centrosome-templated microtubule nucleation
Cellular component: centriolar subdistal appendage; centriole; centrosome; ciliary basal body; mitotic spindle; pericentriolar material; spindle pole; ciliary transition fiber; cytoplasm; desmosome; microtubule; mitotic spindle pole
Genetic constraint (gnomAD): Loss-of-function variants: 124 observed, 232.11 expected, observed/expected ratio (o/e) 0.53, 90% interval 0.46 to 0.62. The upper end of that interval is the gene's LOEUF score, 0.62, which puts it in group 2 of 6, group 1 being the genes least tolerant of losing a copy. Missense variants: 2,255 observed, 2,419.8 expected, observed/expected ratio (o/e) 0.93, 90% interval 0.9 to 0.96. Synonymous variants: 850 observed, 902.84 expected, observed/expected ratio (o/e) 0.94, 90% interval 0.89 to 1.
Homologues: Orthologues: chimpanzee NIN (99% identical), macaque NIN (97% identical), pig NIN (87% identical), dog NIN (86% identical), guinea pig NIN (82% identical), rat Nin (79% identical), mouse Nin (78% identical), rabbit NIN (77% identical), tropical clawed frog nin (48% identical), zebrafish nin (27% identical), Drosophila melanogaster Nin (13% identical), Caenorhabditis elegans noca-2 (7% identical). Paralogues in human: NINL (20% identical).
Diseases named in the same sentence as NIN in open-access papers:
NIN is named in the same sentence as 35 diseases in open-access papers, as found by Europe PMC text mining. Sharing a sentence is not in itself a finding about the gene and the disease. The quoted sentences say what the papers report.
Seckel syndrome (10 papers, 2015 to 2025). A rare autosomal recessive inherited syndrome caused by mutations in the ATR gene, RBBP8 gene, CENPJ gene, CEP152 gene, CEP63 gene, NIN gene, DNA2 gene, or TRAIP gene. "Ninein-knockout mice have a defective epidermal barrier, and bone deformation and mutated forms of ninein have been associated with Seckel syndrome, which is characterized by dwarfism and cognitive deficiencies." (PMID 40113042, 2025). "In humans the rare disease Seckel syndrome-7 (SCKL7) is caused by missense mutations in the NIN gene." (PMID 27422905, 2016). "We expect that our analysis of NOCA-1 may inform studies of vertebrate ninein, mutations in which have been implicated in the human disorders microcephalic primordial dwarfism and spondyloepimetaphyseal dysplasia." (PMID 26371552, 2015). "The importance of the centrosomal protein ninein in development is evident through studies showing that it influences neurogenesis, angiogenesis and stem cell fate, and that Nin gene mutations cause human disorders such as microcephalic primordial dwarfism and spondyloepimetaphyseal dysplasia." (PMID 28179500, 2017). "Seckel syndrome is genetically heterogeneous, and mutations in DDR genes (ATRIP and ATR), DNA repair factors (NSMCE2, DNA2, TRAIP and CtIP) and components of the centrosome (NIN, CEP63, CEP152 and CENPJ) have been reported." (PMID 32994318, 2020). "We are currently determining whether these cellular functions of ninein are of importance for any other tissues during development and whether they are of significance for the pathogenesis of Seckel syndrome." (PMID 30923192, 2019). "Other forms of Seckel syndrome are caused by mutations in genes associated with cell growth (TRAIP), genomic integrity and repair (ATR, NSMCE2, DNA2, and RBBP8), centrosome function (NIN, CEP63)." (PMID 29504900, 2018). "Mutations in the ninein gene have been linked to Seckel syndrome, a recessively transmitted human disorder that leads to primordial dwarfism, microcephaly, cognitive defects, and increased sensitivity to genotoxic stress, but the roles of ninein in this pathogenesis are not understood." (PMID 30923192, 2019).
periodontitis (4 papers, 2014 to 2022). An acute or chronic inflammatory process that affects the tissues that surround and support the teeth. "Genome-wide association studies showed the relationship of NIN, ABHD12B, WHAMM, AP3B2, and SIGLEC5 with chronic periodontitis." (PMID 36360171, 2022). "It is unclear how NIN, which is important for anchoring microtubules for centrosomal function, may affect periodontitis." (PMID 24347629, 2014). "Aside from the SOS2 to NIN region on chromosome 14, none of the other nine implicated loci overlapped with results from published GWAS of periodontitis." (PMID 24347629, 2014). "Because the underlying molecular mechanisms of periodontitis are still largely unclear, the effects of the NIN and SIGLEC5 genes on periodontitis have not been clarified, although significant associations with periodontitis were identified in the European population." (PMID 30765789, 2019). "Since the underlying molecular mechanisms of periodontitis are still unclear, the effects of the NIN, ABHD12B, WHAMM, AP3B2, and SIGLEC5 genes on periodontitis have not been elucidated." (PMID 36360171, 2022).
microcephaly (3 papers, 2014 to 2025). A congenital or acquired developmental disorder in which the circumference of the head is smaller than normal for the person's age and sex. "In this study, we report a patient with short stature, microcephaly and hearing loss with a novel homozygous variant in the NIN gene." (PMID 40751525, 2025). "There is one report of two sisters with severe short stature, microcephaly, and developmental delay with compound heterozygote missense variants in the NIN gene and one paper reporting a homozygote variant in the NIN gene with progressive, high-frequency sensorineural hearing loss in four siblings." (PMID 40751525, 2025). "Notably, another candidate gene, NIN, which functions in the maintenance of asymmetric divisions of neural progenitor cells, and has not been linked to microcephaly, also shows a signature of adaptive molecular evolution across anthropoid primates." (PMID 24898820, 2014). "Moreover, mutations or absence of ninein lead to defects in neural tissue and to microcephaly." (PMID 30923192, 2019).
spondyloepimetaphyseal dysplasia (3 papers, 2015 to 2025). An osteochondrodysplasia that results in abnormalities of bone growth in the vertebral column, epiphysis, and metaphysis. "The only other report is of four members of a consanguineous family with spondyloepimetaphyseal dysplasia with joint laxity-leptodactylic type (SEMDJL2) with a homozygous variant in the NIN gene." (PMID 40751525, 2025).
developmental delay (2 papers, 2024 to 2025). "A significant SNP associated with breast muscle percentage was located within the NIN gene, which has been reportedly implicated in developmental delay and short stature and skeletal deformities in humans, as well as embryonic development in goats." (PMID 38706792, 2024).
Hearing Loss (2 papers, 2019 to 2025). "Based on functional studies, they postulated that variants in NIN could be responsible for hearing loss." (PMID 40751525, 2025).
atopic dermatitis (1 paper, 2019). "The mild barrier defects in the skin of newborn ninein-knockout mice are reminiscent of defects found in skin disorders such as atopic dermatitis, where reduced protein levels of filaggrin and defects in the cornified layer have been implicated in pathogenesis." (PMID 30923192, 2019).
autoimmune disorders (1 paper, 2023). "Antibodies against NIN are present in sera from several patients with SSc and other autoimmune disorders, which further supports a role for NIN in SSc." (PMID 36803404, 2023).
brain malformations (1 paper, 2024). "For example, homozygous mutations in NIN and KIF2A, encoding two components of the subdistal centriolar appendage, are linked to Sickler syndrome type 7 (OMIM 614851) and a syndrome of complex brain malformations (OMIM 615411), respectively." (PMID 38300321, 2024).
breast carcinoma (1 paper, 2016). "C14orf166 interacts with ninein to block the phosphorylation of ninein catalyzed by GSK-3β, suggesting C14orf166 may inhibit ninein, and activate JAK2 to promote breast cancer progression, but this speculation remain to be confirmation." (PMID 26883017, 2016).
colitis (1 paper, 2025). Inflammation of the colon. "In conclusion, our results indicate that NIN can significantly improve the symptoms of colitis caused by UC in mice, reduce colonic tissue damage, improve inflammatory response, and promote mucosal repair." (PMID 40430964, 2025).
Dandy-Walker malformation (1 paper, 2024). "In this study, there was one case of Dandy-Walker malformation with a pathogenic variation in the NIN gene." (PMID 39850204, 2024).
deafness (1 paper, 2025). An inherited or acquired condition characterized by the complete loss of the ability to hear from one or both ears. "This is the first report of a patient with MPD and deafness associated with the NIN gene." (PMID 40751525, 2025).
dermatitis (1 paper, 2019). An inflammatory process affecting the skin. "A different set of more severe human skin disorders, but with molecular defects that resemble our ninein-knockout, have been reported from patients with mutations in the genes encoding desmoglein 1 or desmoplakin, leading to desmosomal defects and to dermatitis." (PMID 30923192, 2019).
glioma (1 paper, 2010). A benign or malignant brain and spinal cord tumor that arises from glial cells (astrocytes, oligodendrocytes, ependymal cells). "Comparing with normal human brain tissue, most of the mRNAs expression in gliomas for centrosomal structural proteins, including centrin 3, γ-tubulin, and hNinein isoforms 1, 2, 5 and 6, Aurora A and Aurora B were elevated." (PMID 20529377, 2010). "Centrosomes were visualized in the glioma samples using confocal microscopy of tissue sections to visualize γ-tubulin and hNinein expression." (PMID 20529377, 2010).
infection (16 papers, 2013 to 2023). The state of being infected such as from the introduction of a foreign agent such as serum, vaccine, antigenic substance or organism. "NIN was the first transcription factor identified as functioning in Lotus japonicus nodulation, and mutation of L. japonicus NIN blocks infection and prevents nodule organogenesis." (PMID 32908854, 2020). "Loss of function of NIN leads to excessive root hair curling, and infection thread formation is blocked." (PMID 32664480, 2020). "The first insight that other, more remote, promoter elements are involved in the induction of NIN in inner layers came from studies with the nin weak alleles daphne (Lotus) and daphne-like (Medicago), in which the infection process is induced but nodule organogenesis is blocked." (PMID 32664480, 2020). "NFR1 and NIN are involved in signal recognition, infection thread formation and other processes during the early development of root nodules." (PMID 36035684, 2022). "NFR1 and NIN are involved in the early nodulation processes, such as the identification of nodulation factors and infection line formation." (PMID 36035684, 2022). "This activation leads to the development of the infection program in epidermis cells, where the NIN, NF-YA1, and ERN1 transcription factors bind with a whole complex of additional regulators based on Chip-seq analysis." (PMID 35009060, 2021). "NIN is essential for nodule initiation, including infection thread formation, nodule organogenesis and AON." (PMID 32664480, 2020). "A 5-kb long promoter including the CYCLOPS binding site driving NIN expression can restore infection thread formation in a nin knockout mutant." (PMID 32664480, 2020). "It was assumed that the CYCLOPS binding site results in a higher expression level of NIN, and the initiation of infection thread formation requires a higher threshold level than curling." (PMID 32664480, 2020). "This suggests that the role of NIN in infection thread formation is conserved in both legumes and actinorhizal plants." (PMID 32664480, 2020). "It is important to note that several BELL genes were found in the ChIP-seq analysis of legume plants as possible targets of the NIN transcription factor, which is one of the most important regulators of nodule organogenesis and infection." (PMID 33419376, 2020). "This suggests that the involvement of a NIN-NF-Y module in intracellular infection, and nodule organogenesis is conserved within the NFC and it evolved at an early moment during nodule evolution." (PMID 32664480, 2020). "Since the NIN transcription factor plays a central role in nodule organogenesis and infection processes, the search for additional BELL genes that are regulated by this protein is of great interest." (PMID 33419376, 2020). "NIN transcription factor is essential for rhizobial entry via infection threads in the epidermis." (PMID 35009060, 2021). "In several legumes, the role of NIN in forming infection threads has been well studied." (PMID 32664480, 2020). "So, NF-Y might, by regulating auxin biosynthesis genes, stimulate entry into the cell cycle, which is involved in both infection and organogenesis, and this also holds for NIN, which regulates NF-Y expression." (PMID 32664480, 2020). "Therefore, the ancestral function of NIN in the epidermis is probably the induction of the production of the mobile signal, whereas its role in infection thread formation evolved later." (PMID 32664480, 2020). "Its expression is regulated by NIN, and it is highly induced at infection sites." (PMID 32664480, 2020). "Similarly, NIN also most likely plays a role in infection of the actinorhizal plant, as it has been shown to be required for Frankia-induced root hair deformation in Casuarina glauca (Casuarina)." (PMID 32664480, 2020). "Upon inoculation, NIN is induced in the epidermis, where it is required for infection." (PMID 32664480, 2020).
infection (continued). "Furthermore, the differential regulation of nodulation-suppressing CLE peptides in L. japonicus and M. truncatula is dependent on the cytokinin-induced action of NIN, a transcription factor required for infection thread and nodule primordia formation." (PMID 30135694, 2018). "Similarly, methyl jasmonate applied to the shoots inhibited the formation of infection threads, NIN gene expression, reduced nodule number and nodule fresh weight, and suppressed nodule development in L. japonicus." (PMID 26460857, 2015). "Finally, the NIN transcription factor may activate its downstream targets related to infection development: the components of heterotrimeric CCAAT-box-binding factor complex, the nuclear factor Y proteins (NF-Ys)." (PMID 35009060, 2021). "In addition, MtNlp1 may directly interfere with infection by blocking NIN’s function." (PMID 34764268, 2021). "Since NIN, ERN and NSP2 are all transcription factors required for infection, it is likely that they would act downstream of the calcium signalling events." (PMID 24015832, 2013). "Likewise, the transcriptional regulators CYCLOPS, NIN, NSP1 and NSP2 are required for the epidermal initiation of infection thread development." (PMID 28230048, 2017).
tumor (4 papers, 2015 to 2024). "We further checked the gene expression in primary tumor versus normal tissue for genes JAK2, PRDM16, LRP1B, NIN, and NKX2-1 with variants repeatedly enriched in variant-based analysis, and, FANCE, enriched in gene-based burden testing, using the TCGA database." (PMID 35954343, 2022). "Interestingly, the tumor driver NIN changes from a protein coding to a non-coding isoform in THCA." (PMID 25578962, 2015). "It is noteworthy that PDRWH also identified known tumor-specific drivers that were missed by other methods, such as ABL2 for BRCA, SETBP1 for KIRC, NIN and TOP2A for STAD." (PMID 38683860, 2024).
NIN also shares sentences with these, for which no sentence is quoted: cancer (4 papers); chronic periodontitis (3); primordial dwarfism (2); adenocarcinoma (1); asthenozoospermia (1); autism (1); chronic myelogenous leukemia (1); cognitive defects (1); dwarfism (1); epilepsy (1); Hip dysplasia (1); Intellectual disability (1); leukemia (1); neurodegenerative disease (1); Seckel syndrome 7 (1); skeletal dysplasia (1); ulcerative colitis (1); viral infection (1).